MUC1 (mucin 1, cell surface associated)
Diseases named in the same sentence as MUC1 in open-access papers (continued):
Sharing a sentence is not in itself a finding about the gene and the disease.
tumor (continued). "All tumor lines which expressed MUC1 in vitro prior to inoculation continued to express MUC1 in the tumor digests." (PMID 26788922, 2016). "In contrast, in vitro re-stimulation of the MUC1-hyperimmune T-cells with B16.MUC1 lysate-pulsed DCs prior to the Winn assay rendered them therapeutically active and prevented tumor outgrowth." (PMID 26788922, 2016). "CellProfiler was used to calculate the proportion of each tumor with MUC1 expression, EGFR expression, MUC1/EGFR co-expression as well as the intensity of associated staining." (PMID 27092881, 2016). "These properties have made the MUC1 TAA a major focus in developing antigen-specific immunotherapies for multiple tumor types." (PMID 27825118, 2016). "Initial characterization of MUC-1 xenografts and subsequent comparison with the commonly available tumor models for ACC revealed a molecular profile distinct from that of NCI-H295R, SW-13 and SJ-ACC3." (PMID 27764813, 2016). "Altered glycosylation of mucin 1 (MUC1) on tumor cells compared to normal epithelial cells was previously identified as an important antigenic modification recognized by the immune system in the process of tumor immunosurveillance." (PMID 27754373, 2016). "In tumor cells, increased tyrosine phosphorylation of MUC1-CT leads to interactions with new proteins, some of which are also aberrantly expressed in cancer." (PMID 27754373, 2016). "In most cases, priming of MUC1-specific CD8+ T cells is thought to be through cross-presentation of vaccine glycopeptide CD8+ epitopes on MHC class I. The tumor-specific MUC1 peptides presented on class I MHCs of tumor cells are hypoglycosylated." (PMID 27472370, 2016). "We have analyzed some of the mechanisms responsible for the effect of altered MUC1 glycosylation on the tumor microenvironment." (PMID 27754373, 2016). "Accordingly, MUC1 is expressed by most epithelial cells and is overexpressed in multiple tumor types." (PMID 27669306, 2016). "Aberrant glycosylation of MUC1 also inhibits its processing as a tumor antigen by DC and presentation to T cells." (PMID 27754373, 2016). "Subsequently, we examined the potential role of MUC1 within the tumor microenvironment by analyzing the number of infiltrating TAMs." (PMID 27276704, 2016). "In contrast, no cleavage restrictions were evident when lysates were employed, even though all MUC1 peptides in tumor lysate are intrinsically embedded." (PMID 26788922, 2016). "We demonstrate here that translation of MUC1 mRNA in an alternate reading frame generates MUC1-ARF protein, which differs in its entirety from the amino acid sequence of its tumor-associated 'parent' protein, MUC1-TM." (PMID 27768738, 2016). "Tumor-specific forms of MUC1 promote tumor cell adhesion to the endothelium through interactions with E-selectin and the intercellular adhesion molecule-1 (ICAM-1), two receptors expressed on the surface of endothelial and peritumoral stromal cells." (PMID 27754373, 2016). "Again, antigen presentation was enhanced for both anti-tumor antibody production and generation of MUC1-reactive CD4+ T cells." (PMID 27472370, 2016). "In contrast, MUC-1 tumors showed significantly elevated levels of EGF-R in comparison to the other tumor models." (PMID 27764813, 2016). "Hypo-glycosylation exposes the VNTR peptide core creating tens to hundreds of repeated, cancer-specific epitopes on each MUC1 molecule, which are commonly expressed on various tumor types among most patients." (PMID 27545199, 2016). "Employing clinically relevant mouse models, we ruled out such causes as irreversible T-cell tolerance, inadequate avidity, and failure of T-cells to recognize aberrantly glycosylated tumor MUC1." (PMID 26788922, 2016). "Numerous other findings demonstrate the key role of abnormal MUC1 and related glycosyltransferases in tumor progression and metastasis." (PMID 27754373, 2016).
tumor (continued). "Given the known role of these proteins in modulating migration, invasion, and tumor progression, we explored the effects of MUC1 on AP-1 dimer formation and function." (PMID 27220889, 2016). "During these studies, one xenograft (MUC-1) displayed marked engraftment and sustained tumor growth." (PMID 27764813, 2016). "We also tested the effect of solamargine on tumor growth and expression of MUC1 in xenografted nude mouse model." (PMID 27830724, 2016). "As a well-established transcript form of MUC1, MUC1/Y has important functions in tumour initiation and progression." (PMID 27287498, 2016). "From the repertoire of MUC1 vaccine-specific antibodies that we isolated, it is clear that this epitope is highly immunogenic in humans as well as being highly tumor-specific in its expression." (PMID 27545199, 2016). "In fact, both peptide-primed and lysate-primed T-cells proved capable of cross-recognizing whole cell MUC1-expressing tumor digests at a higher frequency than non-MUC1 expressing digests." (PMID 26788922, 2016). "The short glycans on the tumor MUC1 directly bind inflammatory cells leading to tumor cell detachment from the primary tumor site and migration to a secondary site." (PMID 27754373, 2016). "Previous studies have shown that MUC1 aptamer can serve as an effective tumor-targeting ligand for selective delivery of anticancer drugs to tumor cells." (PMID 27203221, 2016). "Both WT and MUC1.Tg mice that rejected the primary tumor challenge were rechallenged with B16.MUC1 from 75 to 200 days thereafter." (PMID 26788922, 2016). "On tumour cells MUC1 is posttranslational modified leading to an exposure of the TF epitope by incomplete O-glycosylation." (PMID 27825375, 2016). "While we detected strong nucleo-cytoplasmic distribution of β-catenin in the NCI-H295R tumor model, the staining appeared weaker and of cytoplasmic localization in MUC-1." (PMID 27764813, 2016). "Remarkably, 3 out of 4 peptides were rendered therapeutically effective if two additional vaccines were given after the B16.MUC1 tumor challenge (p = 0.001)." (PMID 26788922, 2016). "In this review, we discuss the immunological evaluation of different conjugate or synthetic MUC1 glycopeptide vaccines in different tumor or mouse models that have been published since 2012." (PMID 27472370, 2016). "Our studies demonstrated that a diverse array of MUC1 antigen preparations can be deployed effectively as a vaccine, but even the most effective preparations are vulnerable to issues of tumor immunoediting." (PMID 26788922, 2016). "First, it required expression of the tumor antigen MUC-1 in at least 50 % of tumor cells for eligibility." (PMID 27532018, 2016). "The ability of MUC1 based vaccines to protect against MUC1-expressing tumor in either wild type or MUC1.Tg mice have shown a range of effects." (PMID 26788922, 2016). "Immunohistochemical analysis in tumor slides of the different xenografts also confirmed these as well as membranous receptor staining specifically for MUC-1, NCI-H295R and SJ-ACC3 xenografts." (PMID 27764813, 2016). "We explored these issues in a mouse model transgenic for human MUC1 which simulates therapeutic issues such as T-cell tolerance, autoimmunity, and heterogeneity of aberrant glycosylation among relevant tumor models." (PMID 26788922, 2016). "The panel of new human anti-MUC1 antibodies isolated from a MUC1 peptide-vaccinated healthy individual characterized in this study showed exquisite tumor specificity in vitro as well as in vivo safety in the donor from whom they were derived." (PMID 27545199, 2016). "Aberrantly glycosylated mucin 1 (MUC1) is a recognized tumor-specific antigen on epithelial cell tumors." (PMID 27472370, 2016).
tumor (continued). "We observed that rechallenged WT mice consistently rejected tumor rechallenge, whereas rechallenged MUC1.Tg mice displayed outgrowth of B16 tumors that down regulated MUC1 and MHC expression." (PMID 26788922, 2016). "MUC1 has been described to play a role in tissue invasion of tumor cells and the formation of metastases." (PMID 27618037, 2016). "On the contrary, SNCG–gene associated with BC development, demonstrated similar pattern as MUC1/Y, that is higher level of expression in PEBCs when compared with corresponding tumour samples (18.818±1.245 compared with 10.407±1.089)." (PMID 27803125, 2016). "Through multiple types of short glycans simultaneously present in tumors, MUC1 acquires multiple oncogenic properties that control tumor development, progression, and metastasis at different steps of the process of carcinogenesis." (PMID 27754373, 2016). "In general, MUC1 vaccines are well-tolerated, generate tumor-specific T cell responses, and have shown evidence of efficacy in a variety of tumor types." (PMID 27669306, 2016). "The MUC1 (Mucin 1) glycoprotein has many characteristics that make it an ideal tumor antigen for cancer immunotherapy approaches." (PMID 27545199, 2016). "We also observed increased expression of HLA class I antigens and ICAM-1, as well as the TAAs CEA and MUC1 on the surface of tumor cells upon exposure to vorinostat." (PMID 26862729, 2016). "In in vitro experiments, co-cultures of DC precursors with MUC1+ tumor cells inhibited their differentiation and function." (PMID 27754373, 2016). "Two patients with low MUC1 expression and CM patterns had tumor recurrence, resulting in death, while all the other patients survived without recurrence." (PMID 27846863, 2016). "Several attempts have been made to develop cancer vaccines specific binding tumor-associated antigens, including MAGEs, CD20, CTLA-4, and MUC1, with the goal of inducing antigen-specific CTLs for cancer therapy." (PMID 26417929, 2015). "The field would benefit from a comprehensive analysis of how the location and identity of MUC1 TACAs influences anti-tumor immune responses in order to design vaccines which produce optimal humoral and cell-mediated immunity." (PMID 26557640, 2015). "The relationship between MUC1 and tumor characteristics in BC was evaluated in several IHC studies but results of these studies are conflicting." (PMID 26693201, 2015). "Mice with tumors implanted orthotopically into the mouse pancreas were injected with DyLight 650-conjugated anti-MUC1 (CT2) antibody with a single 30 μg dose via the tail vein 7–10 days after tumor implantation." (PMID 25815753, 2015). "Next, we investigated the correlation of tumor form of MUC1 and CIN85 expression levels with lymph node positivity and metastasis." (PMID 25675408, 2015). "In many tumor types, expression of MUC1 correlates with aggressive, metastatic phenotype, limited response to therapy and poor survival." (PMID 25971429, 2015). "ELISA was used to measure the amount of IgG, IgM, and IgA against a tumor-specific MUC1 peptide derived from the extracellular tandem repeat domain of MUC1." (PMID 26693201, 2015). "Serum anti-MUC1 IgM levels were higher in patients who had tumor that was equal or smaller than 2 cm (P = 0.03)." (PMID 26693201, 2015). "Our present study showed that HCC cells affected by oncogene MUC1 undergo transition from the tumor-suppressive TβRI/pSmad3C/p21WAF1 pathway to the oncogenic JNK/pSmad3L/c-Myc pathway." (PMID 25714018, 2015). "Further study demonstrated that the expression of MUC1 is consistent with that of pSmad3L and c-Myc but inverse to that of pSmad3C and p21WAF1, suggesting that MUC1 shifted Smad3 signaling from tumor-suppression to oncogenesis in tumor cells." (PMID 25714018, 2015).
tumor (continued). "As a model for tumour cells expressing underglycosylated MUC1 (uMUC1), we deglycosylated mucin which resulted in a striking difference between the treated and untreated mucin, with the former showing a >75% reduction of CEST signal from 0.5 to 2 p.p.m." (PMID 25813863, 2015). "Previously, we reported in a small group of CRC patients that MGL specifically recognizes the tumor-derived mucin MUC1 via binding to the Tn antigen." (PMID 26172302, 2015). "Our data demonstrate that this kind of MUC1 peptide displacement/insertion in the CTB pentamer can induce MUC1-specific CTLs result in MUC1+ B16 tumor protective efficacy and therapeutic efficacy." (PMID 26417929, 2015). "In this study, we have demonstrated that mucCEST MRI is able to differentiate between tumour cells that are expressing normal versus underglycosylated MUC1." (PMID 25813863, 2015). "Fluorescence immunostaining was performed on frozen tumor samples made from BxPC-3 and showed fluorescence on cell membranes demonstrating the expression of MUC1." (PMID 25815753, 2015). "We found that AptMUC1-conjugated gold nanoparticles immobilized, through hydrophobic and π–π interactions, on graphene oxide (AptMUC1–Au NPs/GO) bound effectively to MUC1 units on tumor cell membranes." (PMID 25973571, 2015). "To assess the level of the six tumor markers (MUC1, EMA, Pan-CK, HSP90, TGF-β and CA125), we performed the well-based RPPA with all ascites and pleural effusions." (PMID 26022333, 2015). "Our results warrant a larger study on anti-MUC1 antibodies in NAF to validate the relationship between tumor aggressiveness and immune biomarkers." (PMID 26693201, 2015). "On the other hand, they also showed that MUC1 expression was higher in lymph node metastases when compared to primary tumor tissue." (PMID 26693201, 2015). "Several lines of evidences have demonstrated that MUC1 expression is correlated with tumor proliferation, metabolism, invasion, metastasis, angiogenesis and resistance to apoptosis." (PMID 26367866, 2015). "We chose to use the targeting of a murine tumor expressing MUC1 because the single Ad5 [E1-, E2b-]-MUC1 vector was more potent in some of the murine T-cell assays compared to Tri-Ad5 than the CEA and brachyury vectors compared to Tri-Ad5." (PMID 26374823, 2015). "The second objective of this study was to investigate relationship between anti-MUC1 antibody levels in NAF as a predictive marker for tumor aggressiveness." (PMID 26693201, 2015). "Being that we had shown the importance of the MUC1/CIN85 complex in tumor cells, we questioned if the activities of that complex were also dependent on the presence of Cbl." (PMID 25675408, 2015). "Increased levels and altered glycosylation of MUC1 facilitate invasive growth and metastasis of tumor cells." (PMID 25675408, 2015). "We used a qPCR assay to detect tumor-infiltrating lymphocytes, Th1 responses, and MUC1 expression in tumor tissues from different immunized groups." (PMID 26417929, 2015). "Cancer nests in control group kept active proliferation with plentiful MUC-1+ tumor cells scattering and sparse NK-1+ lymphocytes surrounding tumor milieu." (PMID 26512920, 2015). "In tumor cells, MUC1 is underglycosylated and located in the cytoplasm in addition to the cell membrane, and this depolarized expression is associated with poor prognosis." (PMID 26492273, 2015). "MUC1 cytoplasmic tail can interact with many signaling pathways, and act as a co-transcription factor to activate various genes involved in tumor progression and metastasis." (PMID 25971429, 2015). "In our patients, antibodies against CEA, NY-ESO-1, survivin or MUC-1 frequently decreased in patients with signs of anti-tumor efficacy." (PMID 25714011, 2015). "All but two of the MUC1 expressing tumours stained with 1B9 demonstrating the presence of the T glycan on MUC1 in the same tumours that express Tn." (PMID 25951175, 2015).
tumor (continued). "MUC1.Tg mice showed higher tumor incidence and decreased survival when compared with wild-type mice." (PMID 25675408, 2015). "Increased MUC1 sialylation is thought to be responsible for decreased cell-cell adhesion and thus facilitate tumor cell detachment from primary sites." (PMID 25850034, 2015). "In this study, we found that graphene oxide (GO) modified with Mucin1 (MUC1) binding aptamer–conjugated gold nanoparticles (AptMUC1–Au NPs/GO) coupled with LDI-MS is a facile platform for the detection of tumor cells and for tissue imaging." (PMID 25973571, 2015). "Conversely, MUC1 gene silencing in MUC1 expressing HCC cells results in preserved tumor-suppressive function via pSmad3C, while eliminating pSmad3L-mediated oncogenic activity both in vitro and in vivo." (PMID 25714018, 2015). "To further prove that the CEST contrast originated from the glycosyl groups, we performed experiments on chemically deglycosylated mucin, to mimic the underglycosylated MUC1 present on malignant tumour cells." (PMID 25813863, 2015). "We then evaluated the expression of human tumor MUC1 (detected by anti-MUC1 VU 4H5 antibody), CIN85 and Cbl in the colonic tissue of AOM/DSS-treated mice by immunohistochemistry." (PMID 25675408, 2015). "The conjugated anti-MUC1 antibody bound the tumor in orthotopically-transplanted Panc-1 and BxPC-3 models enabling the tumors to be imaged." (PMID 25815753, 2015). "The most relevant result in tumor is the interaction between MGL, expressed by DCs, and tumor through the Tn glycans expressed by MUC1 tumor associated antigen." (PMID 26839900, 2015). "In the subcutaneous tumor models, the fluorescent signal from the conjugated anti-MUC1 antibody was noted around the margin of the tumor and space between the cells." (PMID 25815753, 2015). "In conclusion, the study presented here demonstrates that our design can activate MUC1-specific CTLs result in tumor suppression in mice." (PMID 26417929, 2015). "Tumor cells MUC-1 positive index was very low in PMSB groups, with only about 1/9 ~ 1/10 of control group, indicating in situ CSC pool was selectively depleted." (PMID 26512920, 2015). "After 3 dose vaccinations, CTB-MUC1-alum-CpG formulation significantly inhibit tumor growth compared with mice given CTB-irrel-CpG (Pep-irrel) or CTB∞MUC1-alum-CpG formulation." (PMID 26417929, 2015). "Tumor expression of MUC1 is correlated with reduced survival of renal cell carcinoma patients and increased metastatic ability of many cancers." (PMID 26557640, 2015). "The compound selectively binds to tumor cells expressing MUC-1, undergoes internalization, and delivers high cytotoxic dose of beta radiation to the tumor cells." (PMID 26369833, 2015). "Evaluations after periodic acid-Schiff staining and immunohistochemical labeling with antibodies against Muc-1 showed that the tumor was solid with trabecular/insular growth patterns and cystic with mucus-secreting cells." (PMID 25229469, 2014). "The first cloned, MUC1, has been reported to be one of the most important human tumor antigens, namely, the second ranking next to WT1." (PMID 25551773, 2014). "Previous studies have reported significant associations between serum MUC1 and VEGF levels and tumor response, PFS and OS in patients with advanced NSCLC treated with EGFR-TKIs." (PMID 25410981, 2014). "Four tumor cell lines, H1650, BT20, HCC1419 and SK-Mel-28, were selected because they expressed alternative cancer associated surface markers including Trop2, Muc1, Her2 and MelCAM." (PMID 24489774, 2014).